BMP4 (bone morphogenetic protein 4)
Diseases named in the same sentence as BMP4 in open-access papers (continued):
Sharing a sentence is not in itself a finding about the gene and the disease.
breast carcinoma (continued). "The findings here reported suggest that vimentin, BMP-2, BMP-4, and SDF-1 could be independent prognostic biomarkers in breast cancer, providing insights beyond traditional clinical factors." (PMID 39859358, 2025). "In breast cancer, CHRDL1 inhibits BMP4-induced cell migration." (PMID 40230414, 2025). "Immunohistochemical analysis was performed to evaluate the expression of vimentin, BMP-2, BMP-4, RANKL, Runx2, OPN, PTX3, and SDF-1, while Kaplan—Meier plots were used to assess their prognostic impact on overall survival in a dataset of 2976 breast cancer patients." (PMID 39859358, 2025). "Here, we analysed a breast cancer xenograft with or without enforced expression of BMP4 to gain insight into the mechanisms by which BMP4 suppresses metastasis." (PMID 39273106, 2024). "The BMP4 upregulated gene, MYO1F, was shown to be a potent suppressor of breast cancer metastasis." (PMID 38689334, 2024). "Some non-canonical BMP4 target genes identified in this study, such as EPHA3 and SORL1, have been implicated in the progression of breast cancer." (PMID 38689334, 2024). "BMP2, BMP4, GDF15 and TGFBR1 were significantly correlated with T stage of breast cancer." (PMID 37333824, 2023). "In contrast, BMP4 may act as an autocrine mediator to activate SMAD7 and block metastasis in animal models of breast cancer." (PMID 35846378, 2022). "Having shown that BMP4 acts as a differentiation factor in both normal and cancer cells, able to decrease BCSC numbers, we then investigated its potential as a predictive molecular marker for breast cancer patients." (PMID 33649296, 2021). "Especially, BMP4 and BMP7 are two common objects of dormancy study with mouse models, in which it has been discovered that BMP4 could induce dormancy of breast cancer and BMP7 could induce dormancy of prostate cancer." (PMID 34712663, 2021). "BMP4 and C3 were significantly expressed in normal tissue as compared to cancerous breast cancer tissues whereas CXCL13 and DKK1 is observed to be expressed in breast cancer tissue as compared to normal breast tissue." (PMID 34754042, 2021). "Similarly, miR-21 has been found to be upregulated in many carcinomas, including PCa and TGFβ/BMP4-induced pri-miR-21-processing, and upregulation of the mature miR-21 was also observed in MDA-MB-468 breast carcinoma cells." (PMID 32182839, 2020). "The expression levels of Jagged-1 and BMP-4 were not higher in breast cancer compared to those in paired normal tissue." (PMID 31409851, 2019). "Interestingly, all the 13 breast cancer cell lines that expressed GREM1 co-expressed at least one of the three BMPs, with BMP4 being most commonly co-expressed." (PMID 31694641, 2019). "To investigate a potential involvement of the BMP family in telomerase activity, we examined the effects of BMP2, BMP4, BMP5, BMP6 and BMP7 on telomerase activity by spiking the medium of cultured human breast cancer MCF-7 cells with purified recombinant human cytokines." (PMID 27696331, 2017). "BMP-4, BMP-6, and BMP-9 have been reported to inhibit metastasis in breast cancer." (PMID 27661009, 2016). "Interestingly, recombinant BMP-4 suppressed constitutive and PMA-induced MMP-9 expression in both fibrosarcoma and breast cancer cells." (PMID 25897433, 2015). "Similarly, Guo and colleagues demonstrated increased migration and decreased proliferation upon BMP4 overexpression in MDA-MB-231 and MCF-7 breast cancer cells." (PMID 24053318, 2013). "An additional finding that could be inferred from our data is that induction of gene transcription, compared with inhibition, was the common response among those genes most frequently regulated by BMP4 and BMP7 in breast cancer cells." (PMID 22118688, 2011). "Patient samples from this study were previously used to identify a four-marker panel including PITX2, BMP4, FGF4, and C20orf55 which enabled outcome prediction in lymph node-positive, HER-2-negative breast cancer patients treated with anthracycline-based chemotherapy." (PMID 20515469, 2010).
breast carcinoma (continued). "Indeed, BMP4 was previously demonstrated to promote cell proliferation in TNBC MDA-MB-231 cells, while in contrast, it was reported to induce cell cycle arrest in MCF-7 human breast cancer cells." (PMID 40001874, 2025). "We did not assess whether the migration of 231HM cells +/− BMP4 is altered by statin treatment in vitro, since previously we have reported that BMP4 does not alter the migration of breast cancer cells." (PMID 39273106, 2024). "Likewise, an IHC study of a tissue microarray from 535 breast cancer patients’ samples displayed low BMP4 protein levels in DCIS and IBC as compared to benign breast tissues thus suggesting a metastasis inhibitor role mediated by BMP4." (PMID 36510219, 2022). "Besides, a study showed that bone morphogenetic protein 4 (BMP4) could promote HCC1954, MDA231 and MDA-361 these three breast cancer cells migration but showed reverse effect on T-47D breast cancer cells." (PMID 33854616, 2021). "In addition, BMP-4 upregulated the sphere forming efficiency, colony formation efficiency, and the expression of cancer stem cell markers, such as Nanog and CD44, in the breast carcinoma cell line MDA-MB-231." (PMID 31409851, 2019). "Interestingly, this may be supported by the finding of increased transcript levels of BMP-4 and its receptor BMPRII in the peripheral blood of breast cancer patients in advanced disease." (PMID 28733469, 2017). "In breast cancer cells, the specific induction of active BMP-4 is exclusively observed in breast cancer cells expressing NDRG2 but not in control breast cancer cells, and NDRG2 expression inhibits the mRNA expression of several MMPs and the gelatinolytic activity of MMP9." (PMID 26506239, 2016). "However the role of bone morphogenetic protein 4 in human breast cancer is not clear, producing opposing effects on different human breast cancer cell lines." (PMID 21080969, 2010). "Furthermore, higher levels of BMP2, BMP6 and GDF5 were revealed in triple negative breast cancer (TNBC) whilst BMP4, GDF15, ACVR1B, ACVR2B and BMPR1B were relatively higher in Luminal type BC." (PMID 37333824, 2023). "However, it is still not known whether EMT induced by BMP-4 is able to enhance stem cell properties both in mammary epithelial cells and breast cancer cells." (PMID 31409851, 2019). "Collectively, these data suggest that BMP-4-mediated signaling is associated with the activation of Notch signaling in patients with breast cancer, and that Notch activation is involved in the expression of genes related to cancer stem cell properties and EMT in breast cancer cells." (PMID 31409851, 2019). "Additionally, BMP4 overexpression has been shown to inversely correlate with TBX3 expression in mammary tissues; however, it remains unclear whether this relationship holds true in breast cancer, particularly given that both BMP4 and TBX3 exhibit pro-proliferative properties in breast cancer." (PMID 40001874, 2025). "Of note, BMP4 and BMP7 did not alter the RFP content of the mammosphere cells, and these 3D cultures appeared much closer to controls, which agrees with the previously established pro‐MET action of the BMPs on breast cancer cells." (PMID 35348275, 2022). "However, it is not clear whether BMP-4 signaling and Notch signaling cooperate with each other in order to enhance EMT, metastasis, and tumor recurrence in breast cancers." (PMID 31409851, 2019).
glioma (48 papers, 2013 to 2025). A benign or malignant brain and spinal cord tumor that arises from glial cells (astrocytes, oligodendrocytes, ependymal cells). "Here we use scaffolds of glycopeptide nanostructures designed for regenerative therapies to bind and present bone morphogenetic protein (BMP-4) in vivo to differentiate glioma cells and render them more susceptible to traditional chemotherapeutics." (PMID 41624070, 2025). "BMP-4 is overexpressed in gliomas harboring IDH1 mutations, which are a hallmark of better prognosis." (PMID 35693928, 2022). "The associations of BMP4 expression with clinical-pathological factors and prognosis of glioma patients were also statistically analyzed by Bao and coworkers." (PMID 24877113, 2014). "In the discovery set, BMP4 overexpression was significantly associated with low grade as well as the lower mortality of high-grade gliomas in survival analysis (log-rank, p<0.05 in GBM patients and p<0.01 in anaplastic gliomas, respectively)." (PMID 23590708, 2013). "As BMP4 showed association with LGGs and better prognosis, we screened its expression in different molecular subtypes of gliomas." (PMID 23590708, 2013). "However, high levels of BMP4 have also been shown to be associated with promising survival rates in patients with glioma, as BMP4 promotes glioma cancer stem-like cell differentiation, and in turn, increases the tumor response to radiotherapy and chemotherapy." (PMID 34249928, 2021). "Fstl1, a member of the family, is elevated in high‐grade gliomas and contributes to tumor growth via the BMP4/Smad1/5/8 pathway." (PMID 40781854, 2025). "The BMP4-induced senescence of glioma-initiating cells was accompanied by the increased expression of p21 and was also dependent on p21 expression." (PMID 40725230, 2025). "Overexpression of FSTL1 has been identified as an indicator of an unfavorable prognosis in GBM patients, with research indicating that Fstl1 stimulates glioma growth via the BMP4/Smad1/5/8 signaling pathway." (PMID 40781854, 2025). "Retinoids also oppose Notch and Wnt/β-catenin pathways that maintain glioma stem-cell self-renewal, while simultaneously up-regulating BMP4, a driver of astro-glial differentiation." (PMID 40422249, 2025). "Previously, it was determined that approximately 100 ng/mL of BMP4 is sufficient to induce an anti‐glioma response against BTICs." (PMID 39545093, 2024). "In this study, we focused on IDH wild-type glioma, since BMP4 is generally more downregulated than in IDH mutant glioma, and, therefore, the potential effect size would be maximal." (PMID 39337661, 2024). "Studies in glioma cell cultures and in vivo have already shown that BMP4 indeed induces the differentiation of GSCs together with decreased cell proliferation and apoptosis within the tumor and increased survival in vivo." (PMID 39337661, 2024). "Recent research has shown that bone morphogenic protein 4 (BMP4) can decrease glioma cell proliferation by targeting the CD133+ population of glioma cells that exhibit stem cell-like properties." (PMID 39204078, 2024). "A large study of patients (n = 630) revealed that BMP4 expression was significantly lower in gliomas than healthy patient tissue." (PMID 39545093, 2024). "The FOXO3a/BIM axis has been reported to affect the chemosensitivity of BMP4-differentiated glioma stem cells to temozolomide." (PMID 36718644, 2023). "Jin and colleagues reported the high expression of FSTL1 in high-grade gliomas, and it facilitates glioma growth by negatively regulating the BMP4-Smad signaling." (PMID 36756161, 2023). "In gliomas, delivery of bone morphogenetic protein 4 (BMP4) reduces the GSC pool and elicits the expression of markers of neuronal lineage." (PMID 35610201, 2022). "Expression of BMP4 is decreased in high‐grade glioma compared to low‐grade glioma, and patients with high BMP4 expression show significantly better prognosis than those with low BMP4 expression." (PMID 34214250, 2022).
glioma (continued). "BMP‐4 reduced the expression of glioma stem cell marker mRNAs, including PROM1, OLIG2, and SOX2, in TGS‐01 as well as in TGS‐04 cells." (PMID 34214250, 2022). "Accordingly, several reports have shown that BMP-4 is expressed in low-grade gliomas, and that it serves as a favorable prognostic marker in gliomas." (PMID 35693928, 2022). "The expression of BMP4 is higher in low-grade gliomas, with lower mortality rates as compared to high-grade gliomas." (PMID 36316503, 2022). "Several reports have shown that BMP4 is expressed in low-grade gliomas and that it serves as a favorable prognostic marker in gliomas." (PMID 36778912, 2022). "In this study, we used isolated hGSCs from surgical samples of glioma patients and the established hNSC lines to study their responses to BMP4 treatment." (PMID 36316503, 2022). "We previously reviewed BMP4 signaling in central nervous system development and glioma tumorigenesis and its potential as a treatment target in human gliomas." (PMID 32102285, 2020). "The pre-glioblastoma subtype within isocitrate dehydrogenase 1 (IDH1) mutant gliomas express low BMP4, in comparison to early progenitor-like and neuroblastic subtypes, and is associated with a poor patient prognosis." (PMID 32102285, 2020). "It was also demonstrated that glioma cells exposed to BMP4 showed a significant reduction in the proportion of GSCs, and the in vivo delivery of BMP4 effectively blocked tumor growth." (PMID 32722427, 2020). "As in mice transplanted with control GSCs, mice transplanted with BMP4-treated GSCs developed high-grade gliomas, though with prolonged latencies to tumour formation, compared to control cells (p < 0.01)." (PMID 31602000, 2019). "Our in vitro studies show that the anti-proliferative effect of BMP4 on glioma cells in mediated by its downstream targets, ID1 and p21." (PMID 31602000, 2019). "Differentiation therapy has been exploited with Bone Morphogenetic Protein-4 (BMP4) treatment, to induce glial differentiation and reduce tumor growth in gliomas." (PMID 30895167, 2019). "Activated BMP4 signaling is previously shown to differentiate stem-like cancer cell population in gliomas and colorectal cancer, suggesting it to be key regulator of human tumorigenesis." (PMID 30287850, 2018). "The role of BMP4 is also emerging in oncogenesis, as reported in inducing differentiation of glioma and colorectal cancer stem-cells." (PMID 30287850, 2018). "After intracranial implantation of NHAs, NSCs and NSCs-BMP4 for 1 week, 2 weeks and 3 weeks, the brains of the nude mice bearing xenografted gliomas were sectioned and examined under fluorescence microscopy." (PMID 26908439, 2016). "To determine if hNSCs or BMP4 loaded hNSCs would migrate in response to glioma in vivo, we assayed in vivo migration using a two-color fluorescence labeling approach." (PMID 26908439, 2016). "Next, we examined the effect of NSCs-BMP4/CM on glioma cell migration using the wound-scraping assay." (PMID 26908439, 2016). "A recent clinical study has shown that patients high levels of BMP-4 have a better chance for survival when compared to patients with high-grade glioma who have a lower expression level of BMP-4." (PMID 25897433, 2015). "Mice intracranially injected with untreated glioma cells died after three to four months, but nearly all mice injected with BMP4-treated cells survived until the end of the experiment." (PMID 24877113, 2014). "They evaluated the expression status of BMP4 in a total of 630 patients with glioma and correlated this dataset with clinical prognosis." (PMID 24877113, 2014). "They generated a TMZ resistant U251 glioma cell line and observed a reduction of the BMP4 protein levels." (PMID 24877113, 2014). "The CD133+ GIC fraction used in this study was isolated from the human glioma cell line U87 by using vincristine and was exposed to the BMP4 protein." (PMID 24877113, 2014).
glioma (continued). "We try to investigate the relationship between BMP4 expression and the biological behavior of gliomas in order to lay a foundation for the management of these tumors." (PMID 24099560, 2013). "Differentiation therapy has also been exploited with Bone Morphogenetic Protein-4 (BMP4) treatment to induce glial differentiation reducing tumor growth in gliomas." (PMID 23476653, 2013). "BMP4 expression was independently associated with grade and good prognosis in grade III and grade IV gliomas, suggesting BMP4 as a novel biomarker with potential important therapeutic implications." (PMID 23590708, 2013). "BMP4 is differentially expressed in glioma patients and is closely related to the biological behavior of gliomas." (PMID 24099560, 2013). "We found that the expression of BMP4 in low-grade gliomas was significantly higher than that in high-grade gliomas." (PMID 24099560, 2013). "And it was associated with the better prognosis in grade III and grade IV gliomas, all of which suggested that BMP4 was a novel biomarker with potential important therapeutic implications." (PMID 23590708, 2013). "In the context of gliomas, BMP-4 expression was found to correlate well with lower grade gliomas and better prognosis in grade III and grade IV gliomas (GBM)." (PMID 23800258, 2013). "We further validated the protein expression level of BMP4 in an independent group of 77 glioma patients by IHC." (PMID 23590708, 2013). "All mice infected with untreated glioma cells died after three to four months, but nearly all mice infected with BMP4-treated cells survived." (PMID 24099560, 2013). "In some studies, BMP4 has been observed to promote the differentiation of glioma stem cells, inhibit their proliferation, and decrease tumorigenicity." (PMID 24099560, 2013). "A VACV that expresses BMP-4 was constructed and utilized for infecting several primary glioma cultures besides conventional serum-grown glioma cell lines." (PMID 23800258, 2013). "We studied the relationship between BMP4 expression and the biological behavior of gliomas in order to provide a theoretical basis for the treatment of glioma." (PMID 24099560, 2013). "The overexpression of BMP4 was also detected in low grade gliomas compared to the high grade ones by immunohistochemistry (p<0.05, chi-square test)." (PMID 23590708, 2013). "Oligodentrocytic genes were accumulated in patients with higher BMP4 expression, which was preferentially expressed in Proneural gliomas." (PMID 23590708, 2013). "Considering these studies, one may propose that the (re-) activation of BMP4 signalling might be a suitable strategy to block the stem-like phenotype of adult and juvenile gliomas and thereby sensitize them towards conventional therapy regimes." (PMID 36497175, 2022). "Similar to the role of BMP signaling in neural stem cell differentiation, our data confirm that BMP4 could induce glioma stem cells to differentiate into astrocytes." (PMID 36316503, 2022). "Some groups reported that the inhibition of BMPs only decreases cell growth but cannot affect the stemness of GSCs while others indicated that BMP4 could reduce glioma stemness by inducing their differentiation." (PMID 36316503, 2022). "BMP4 also reduces multidrug resistance in glioma cells and suppresses glioblastoma invasiveness." (PMID 32102285, 2020). "Interestingly, BMP4-triggered differentiation led to downregulation of the same signaling pathways in L0125 and L0615 glioma spheres." (PMID 32788653, 2020). "Increasing evidence indicates that BMP4 signaling pathways are relevant to human gliomas." (PMID 32102285, 2020). "Taken together, these results suggest that BMP4/7 may be explored as potential therapeutic agents for glioma." (PMID 24877113, 2014). "Besides, they determined the protein expression level of BMP4 in an independent cohort of 77 glioma patients by immunohistochemistry (IHC), further demonstrating that BMP4 showed a low grade glioma preference both at the mRNA and protein level." (PMID 24877113, 2014).